USP17L30 (ubiquitin specific peptidase 17 like family member 30)
Description:
Deubiquitinating enzyme that removes conjugated ubiquitin from specific proteins to regulate different cellular processes that may include cell proliferation, progression through the cell cycle, apoptosis, cell migration, and the cellular response to viral infection.
Tractability: No criterion of Open Targets' tractability assessment is met for any kind of drug.
Target class: Enzyme; Hydrolase
Gene: Protein-coding gene on chromosome 4 (9,363,129 to 9,364,721, forward strand). Ensembl gene ENSG00000228856.
Subcellular location: Nucleus, nucleolus; Endoplasmic reticulum
Pathways (Reactome):
Metabolism of proteins: Ub-specific processing proteases
Gene Ontology:
Molecular function: cysteine-type deubiquitinase activity; hyaluronic acid binding; RNA binding
Biological process: positive regulation of epithelial cell apoptotic process; protein deubiquitination involved in ubiquitin-dependent protein catabolic process; regulation of apoptotic process; protein deubiquitination
Cellular component: nucleolus; nucleus; endoplasmic reticulum
Homologues: Paralogues in human: USP17L24 (100% identical), USP17L25 (100% identical), USP17L26 (100% identical), USP17L27 (100% identical), USP17L28 (100% identical), USP17L29 (100% identical), USP17L5 (99% identical), USP17L20 (99% identical), USP17L11 (99% identical), USP17L17 (99% identical), USP17L18 (99% identical), USP17L22 (99% identical), and 59 more.